GOLGA6D (golgin A6 family member D)
Tractability: No criterion of Open Targets' tractability assessment is met for any kind of drug.
Gene: Protein-coding gene on chromosome 15 (75,282,835 to 75,295,530, forward strand). Ensembl gene ENSG00000140478.
Subcellular location (Human Protein Atlas): Vesicles; Centrosome; Nucleoplasm
Gene Ontology:
Biological process: Golgi organization
Cellular component: cis-Golgi network; Golgi cis cisterna; Golgi cisterna membrane; Golgi apparatus
Genetic constraint (gnomAD): Loss-of-function variants: 7 observed, 9.37 expected, observed/expected ratio (o/e) 0.75, 90% interval 0.42 to 1.4. That is too few expected variants to judge how well the gene tolerates losing a copy. Missense variants: 71 observed, 106.84 expected, observed/expected ratio (o/e) 0.66, 90% interval 0.55 to 0.81. Synonymous variants: 26 observed, 40.56 expected, observed/expected ratio (o/e) 0.64, 90% interval 0.47 to 0.89.
Homologues: Orthologues: mouse Golga2 (47% identical), dog GOLGA2 (45% identical), tropical clawed frog golga2 (34% identical), zebrafish golga2 (32% identical), Drosophila melanogaster GM130 (23% identical), Caenorhabditis elegans golg-2 (19% identical), rat Golga2l1 (5% identical). Paralogues in human: GOLGA6C (99% identical), GOLGA6A (99% identical), GOLGA6B (99% identical), GOLGA2 (55% identical), GOLGA8G (53% identical), GOLGA8F (52% identical), GOLGA8S (51% identical), GOLGA8N (49% identical), GOLGA8O (49% identical), GOLGA8Q (48% identical), GOLGA8T (48% identical), GOLGA8K (48% identical), and 6 more.